ESR2 (estrogen receptor 2)
Diseases named in the same sentence as ESR2 in open-access papers (continued):
Sharing a sentence is not in itself a finding about the gene and the disease.
endometriosis (continued). "The risk for the occurrence of endometriosis is evaluated in association with the polymorphisms of various genes, participating in the biosynthesis of estrogens, including CYP19A1 and ESR2." (PMID 33153202, 2020). "The ESR1 and PGR expression levels were substantially lower, while the level of ESR2 gene expression was significantly higher in endometriosis than in normal endometrium." (PMID 33153202, 2020). "Summing up, methylation of the CpG site at the ESR2 promoter region was the main mechanism responsible for the differentiated expression of ESR2 gene, both in endometriosis and in normal endometrium." (PMID 33153202, 2020). "It has a sequence that regulates ESR1 and ESR2 genes, and it is still among the main candidate genes for endometriosis and ovarian cancer." (PMID 32143537, 2020). "ESR2 expression is unchanged in eutopic endometrium from women with endometriosis although one study reported increased ESR2/ESR1 ratio in endometriosis-affected endometrium." (PMID 31387263, 2019). "In fact, one study revealed that MPA can decrease ESR1 and ESR2 while increasing PR-A and PR-B in the endometrium women with endometriosis." (PMID 31387263, 2019). "In that study, ESR2 was the predominant E2 receptor expressed in macrophages from both women with endometriosis and endometriosis model mice." (PMID 31387263, 2019). "Taken together, these findings support an important role for SRC-1 isoform and ESR2 upregulation in the development and progression of endometriosis." (PMID 31387263, 2019). "Since E2′s effects are primarily enacted through ESR1 and ESR2, their expression levels are important in the assessment of E2 action in endometriosis." (PMID 31387263, 2019). "ESR2 upregulation in endometriotic lesions was reproduced in a mouse model of endometriosis, where its activity was shown to drive lesion growth and be an effective target for the inhibition of lesion growth." (PMID 31387263, 2019). "To date, the genetic risk factors for endometriosis-related infertility have also included the ESR1, ESR2, and luteinizing hormone beta-subunit FOXP, complement component 3, lysyl oxidase-like protein 4, and FCRL3 genes." (PMID 28405865, 2017). "To date, the genetic risk factors for endometriosis-related infertility have included the 17β-hydroxysteroid dehydrogenase type 1, ESR1, ESR2, and luteinizing hormone beta-subunit genes." (PMID 23553198, 2013). "This point was already addressed by others who demonstrated that downregulation of DNMT3A and DNMT3B led to regulation of ESR1 or ESR2 via promoter DNA aberrant methylation in acute myeloid leukemia, endometriosis, prostate and ovarian cancer." (PMID 23626723, 2013). "Expression profile of specimens at the border between eutopic endometrium and endometriosis specimens, interestingly, revealed that the overexpressed estrogen receptor 2 (ESR2) is a central linkage to other gene nodes." (PMID 22203846, 2011). "This is an important finding because it shows that the overexpression of ESR2 could be the triggering step that initiates the deregulation of other key genes associated with inflammation, cellular matrix, immune response, growth factors, apoptosis, and others, thus leading to endometriosis." (PMID 22203846, 2011). "To validate whether the PCB126/ESR2 axis drives endometriosis progression, we employed IHEECs overexpressing ESR2 (IHEECs:ESR2) and then determined whether PCB126 enhances the growth of IHEECs:ER2 compared to their parental IHEECs." (PMID 41054802, 2025). "How does PCB126 activate ESR2 in endometriotic lesions to promote endometriosis progression?" (PMID 41054802, 2025). "Additionally, functional validation of the isoform-specific signaling pathways, particularly the MAPK/PI3K/Akt activity in ESR1+ and ESR2+ stromal cells, are needed to determine their roles in endometriosis pathophysiology." (PMID 41000819, 2025). "Targeting the AXL/ESR2/DNMT3A axis may represent a novel therapeutic avenue for environmentally induced endometriosis." (PMID 41054802, 2025).
endometriosis (continued). "Oestrogen also acts via specific receptors, oestrogen receptor-α (ESR1) and oestrogen receptor-β (ESR2), the latter of which has been demonstrated to be overexpressed in women with endometriosis and may play a role in disease development." (PMID 40628402, 2025). "Further investigation of the ESR2/ESR2 ratio in eutopic endometrium from endometriosis patients may reveal its potential role in disease pathogenesis and progression." (PMID 40072055, 2025). "In BMC Medicine, a recent study utilizing gene expression data from endometriosis lesions demonstrates that ovarian endometrioma (OMA) subtype of endometriosis displays the most significant response to estrogen suppression treatment by directly affecting ESR2." (PMID 38816887, 2024). "ESR1 might be involved in the initiation of endometriosis, while the overproduction of estradiol in endometriosis would drive ESR2 signaling to support endometriotic tissue survival and enhance inflammation." (PMID 38892003, 2024). "In a previous report, we showed that Ki67, PGR-T, ESR1, and ESR2 constitute valid biomarkers for endometriosis progression since their levels and patterns of nuclear immunopositivity in ectopic lesions differed significantly from those of corresponding eutopic endometria or non-diseased endometria." (PMID 36788175, 2023). "In contrast, polymorphisms in the estrogen receptor beta (ESR2) but not ESR1 gene are associated with stage IV endometriosis in Japanese women." (PMID 37676242, 2023). "In the studied group of women with endometriosis, a significant increase in the expression of the ESR2 gene was found, which may indicate the participation of this factor in the pathogenesis of endometriosis." (PMID 34638893, 2021). "Aberrant expression of epigenetic alterations in endometriosis include genomic DNA methylation of the gene encoding progesterone receptor-β, HOXA10, ESR2, which are candidate genes responsible for the development of progesterone resistance and implantation failure." (PMID 32658928, 2020). "According to most recent studies, ESR2 and CYP19A1 genes may account for the potential risk factors of infertility associated with endometriosis." (PMID 33153202, 2020). "The literature data on ESR2 gene expression level in endometriosis are rather scarce." (PMID 33153202, 2020). "Indeed, disruption of the SRC-1 isoform-ESR2 access with inhibitors suppressed endometriotic cell growth in isolated human cells and in a mouse model of endometriosis." (PMID 31387263, 2019). "Additional experiments revealed interaction between this SRC-1 isoform and ESR2 in endometriosis that may mediate a synergistic role in promoting cell survival." (PMID 31387263, 2019). "Hypomethylation of SF-1 and ESR2 promoters may be responsible for increased estrogen action in women with endometriosis." (PMID 22233680, 2012). "Furthermore, the analysis supported the potential central involvement of ESR2 in the initiation of endometriosis." (PMID 22203846, 2011). "Thus, we investigated whether PCB126 exposure modulates the SRC-1 isoform/MMP-9/ESR2 axis in endometriotic lesions, enhancing endometriosis progression." (PMID 41054802, 2025). "A rodent model of endometriosis revealed that treatment with candidate miRNA, let-7b resulted in a decrease in endometriotic lesion size and decreased expression of several genes important in the pathophysiology of endometriosis including Esr1, Esr2, CYP19a, and IL-6." (PMID 34244742, 2021). "In consideration of the rather small number of studies on the expression and CYP19A1 and ESR2 gene in patients with endometriosis, the assumed impact of experimental studies may bring a real added value, extending our knowledge of the effects of genetic factors on the development of endometriosis." (PMID 33153202, 2020).
endometriosis (continued). "According to the most recent studies, the following genes may account for the potential risk factors of infertility associated with endometriosis: ESR1, ESR2, beta hormone luteinizing gene, FOXP subunit, complement component 3 gene, and the Fc receptor-like 3 (FCRL3) gene." (PMID 33153202, 2020). "ESR2 is a well-established driver of endometriosis, and PCB126 enhances ESR2 activity through the AXL/GAS6 signaling axis." (PMID 41054802, 2025). "Hormonal treatments for endometriosis primarily target ESR1, ESR2, or PGR and have the highest affinity for these receptors; however, due to the structural similarity of hormone receptors, off-target effects at other receptors are possible." (PMID 37996888, 2023). "Previous studies have reported that the decreased ESR1/ESR2 in ectopic lesions leads to the decreased expression of PGR, which can exacerbate the inflammatory response, thereby contributing to endometriosis." (PMID 36860677, 2023). "It had 15 targets in the endometriosis-related gene set, and some of these targets, such as ESR1, ESR2 and PTGS2, had a high correlation score in MalaCards." (PMID 35130311, 2022). "In a baboon model of endometriosis, decreased ESR1 level was showed in endometrial stromal cells, while reduced ESR-2 expression was displayed in endometrial stromal and glandular epithelial cells." (PMID 36249421, 2022). "Five estrogen-responsive genes, CYP19A1, EGFR, ESR2, FOS, and IGF1, were found to be modified in human endometriosis, uterine tumor and breast tumor tissues." (PMID 36401252, 2022). "Previous research has shown that ESR2 upregulates CCL2 via NF-κB signaling in endometriotic stromal cells and recruits macrophages to promote the pathogenesis of endometriosis." (PMID 34531861, 2021). "The results of experimental study, concerning the analysis of ESR1, ESR2, PGR, and CYP19A1 genes, unveil the existence of certain correlations of their expression with endometriosis." (PMID 33153202, 2020). "ESR2, which is upregulated in OE, has been shown to suppress ESR1 expression in endometriosis by binding to the ESR1 promoter." (PMID 30728052, 2019). "Peritoneal fluid macrophages from women with endometriosis were shown to upregulate the expression of ESR1 and ESR2, and the expression of ESRs correlated with an increase in inflammatory cytokines." (PMID 31387263, 2019). "Our analysis of 557,061 cells across eight unique scRNAseq datasets from endometriosis patients reveals no consistent overexpression of ESR2/ERβ in any cell or tissue type." (PMID 41000819, 2025). "The disease eutopic tissue’s lymphocyte cells comparison was not significant (OR = 0.994), showing that ESR1 and ESR2 are not co-expressed and tend to be uniquely and specifically expressed in endometriosis lymphocytes." (PMID 41000819, 2025). "Learning and understanding the relationships between ESR2 and CYP19A1 gene expression and endometriosis may help design and develop new therapeutic concepts and strategies in the context of the disease." (PMID 33153202, 2020). "Endometriosis has been recognized as a disease accompanied by aberrant methylation and expression of steroidogenic factor-1 (SF-1), estrogen receptor 2 (ESR2), progesterone receptor (PR-B) and HOXA10 genes in the eutopic endometrium of women with endometriosis." (PMID 22233680, 2012). "A significant increase of ESR2 and CYP19A1 gene expression was observed in the studied groups of women with endometriosis, which may indicate a certain role of this factor in the pathogenesis of endometriosis." (PMID 33153202, 2020). "The increase in ESR2 levels in lesions may be responsible for increased lesion survival and inflammation because E2 can act through ESR2 to induce the cyclooxygenase-II (COX-2)-prostaglandin E2 (PGE2) feedback loop, which is well known to increase the inflammation and pathology of endometriosis." (PMID 31387263, 2019).
ovarian carcinoma (106 papers, 2004 to 2026). A malignant neoplasm originating from the surface ovarian epithelium. "Similar correlations have been documented in lung and ovarian cancers, underscoring the role of tissue-specific factors and gene–environment interactions in the pathogenicity of ESR2 variants." (PMID 41153361, 2025). "Our group investigated the influence of single nucleotide polymorphisms (SNPs) in the promoter region of the ESR2 gene encoding ERβ on ovarian cancer risk in 184 ovarian cancer samples." (PMID 37345182, 2023). "Some studies have highlighted the significant role of ESR-2 rs1271572 in the risk of ovarian cancer." (PMID 22808109, 2012). "Description of the studies included in the pooled analysis of the ESR2 rs1271572 and ovarian carcinoma risk." (PMID 21673961, 2011). "Several polymorphisms in ESR2 have been associated with a small increased risk of ovarian cancer." (PMID 32580290, 2020). "Furthermore, our results from a phenotype-genotype association study suggested that the single nucleotide polymorphism rs3020449 in the promoter region of ESR2 gene might affect progression of ovarian cancer." (PMID 30326857, 2018). "Also, genetic susceptibility studies have supported estrogens in the etiology of ovarian cancer, as a single nucleotide polymorphism (SNP) in the ESR2 gene, which codes for ERβ, and which is considered a tumor suppressor, is associated with significantly increased risk of ovarian cancer." (PMID 28674494, 2017). "A potential causal association of rs1271572 with the risk of ovarian cancer is supported by the finding that it maps to the promoter of the ESR2 gene, near (−53 bp upstream) the AP-4/MyoD binding site, a region of predicted intense transcription factor binding that might influence gene expression." (PMID 21673961, 2011). "Expression of ESR-2 in the chicken ovaries is very low and ovarian cancer has been reported to have a higher ESR1/ESR2 ratio in both chicken and women." (PMID 31128594, 2019). "Moreover, some genetic variants are shared, but there are also certain population specificities, such as WNT4, ESR2, and PSEN1 gene polymorphisms, which have been reported to be involved in ovarian cancer in Chinese individuals." (PMID 36685881, 2022). "Genes related to estrogen pathways, including ESR1 and ESR2, their coregulator PELP1, and the SRC, play a role in the induction and progression of ovarian cancer." (PMID 40362695, 2025). "The levels of ESR2 RNA were reduced in adrenocortical carcinoma (ACC), ovarian cancer (OV), pheochromocytoma and paraganglioma (PCPG), and testicular germ cell tumors (TGCTs)." (PMID 38666956, 2024). "In this paper, we explore the expression of four estrogen signaling pathway mediators, ESR1, ESR2, PELP1 and SRC kinase in ovarian cancer patients." (PMID 34207568, 2021). "In contrast to the chemerin protein data from IHC, mRNA levels of the RARRES2 gene in ovarian cancer were not correlated with PGR, ESR2, ESRRA, ESRRB, ESRRG, nor CEACAM5 after analysis of both patient collectives on the mentioned platforms (p > 0.05 for all)." (PMID 36900088, 2023). "Additionally, we investigated the correlation of estrogen-related pathway genes (ESR1, ESR2, PELP1, and c-SRC) with hsa-miR-21 and hsa-miR-145 in non-affected ovary and ovarian cancer." (PMID 40362695, 2025).
colon carcinoma (93 papers, 2009 to 2026). "The two main subtypes of ERs are ERα (encoded by oestrogen receptor 1, ESR1) and ERβ (encoded by oestrogen receptor 2, ESR2), which are differentially expressed in normal colon tissue as well as in colon cancer cells." (PMID 38137047, 2023). "Although the germline ESR2-CA and risk of colon cancer have been associated the instability of this microsatellite in colon cancerous tissue has never been reported." (PMID 36901930, 2023). "Two studies reported gender-specific associations of the ESR2 CA repeat polymorphism with overall survival among patients with metastatic colorectal and colon cancer." (PMID 25376484, 2014). "Yet in another independent study, having two ESR2 alleles with ≥22 CA repeats compared to having two shorter ESR2 alleles with <22 CA repeats was associated with an increased risk of colon cancer among Japanese women." (PMID 25376484, 2014). "The expression of ESR2 splicing variants in colon cancer cells was first reported in 2001." (PMID 29132333, 2017). "In the present study, the germline ESR2-CA genotype and resulting ER-β expression/estrogen activity was suggested to affect the type of colon cancer generated or patients’ age." (PMID 36901930, 2023). "The germline ESR2-CA genotype and resulting ER-β expression/estrogen activity seem to affect the type of colon cancer generated or the age of onset/diagnosis of the disease." (PMID 36901930, 2023). "ESR2 and CHKA are also associated with colon and esophageal cancers, while CRYGC is only directly related to colon cancer according to the GeneCards database." (PMID 33273919, 2020). "Genistein has been found to reduce proliferation of colon cancer cells with high expression of ESR2 and the anti-proliferation effect of genistein depends on binding and activation of ESR2." (PMID 30871032, 2019). "Women harbouring two long alleles (≥25 CA repeats) of the ESR2 CA repeat and men having two alleles with ≥23 CAG repeats in AR were at increased risk for colon cancer compared to individuals with shorter alleles of the respective polymorphism." (PMID 25376484, 2014). "The purpose of this study was to elucidate whether and how ESR2-CA or its instability affects colon cancer pathogenesis, considering the background of patients and tumors." (PMID 36901930, 2023). "Groups including ours previously reported that ER-β gene (ESR2) cytosine-adenine (CA) repeat polymorphism (ESR2-CA) in the germline affected the colon cancer risk in postmenopausal women, but not rectal cancer risk, or colon cancer risk in men and premenopausal women." (PMID 36901930, 2023). "The germline ESR2-CA genotype and resulting ER-β expression were considered to affect the clinical characteristics (age/locus/MMR status) of colon cancer, supporting our previous findings." (PMID 36901930, 2023). "Is a change of the ESR2-CA repeat number, one of MSI, important in the pathogenesis of colon cancer?" (PMID 36901930, 2023). "In the present study, we examined the ESR2-CA and ER-β expression in NonCa and Ca of surgical materials from postmenopausal colon cancer patients, taking the patients’ age, tumor locus, and MMR status into consideration." (PMID 36901930, 2023).